STAT1 (signal transducer and activator of transcription 1)
Diseases named in the same sentence as STAT1 in open-access papers (continued):
Sharing a sentence is not in itself a finding about the gene and the disease.
infection (continued). "Phosphorylation of IRF3 and STAT1 was enhanced when RUNX1 was knocked down, while phosphorylation of IRF3 and STAT1 were markedly decreased in the cells with RUNX1 overexpression compared with the control cells at 3, 6, and 9 h post PR8 infection." (PMID 35248104, 2022). "We found that infection with SFNV and SFSV inhibits STAT1 and 2 phosphorylation." (PMID 35720342, 2022). "In addition, a small group of transcription factors was predicted to be inhibited only upon infection with amastigotes (SOX6, RUNX3, and STAT1) or promastigotes (TRIM24, SIRT1, and FOXP3)." (PMID 35430587, 2022). "The Jak–STAT pathway is thought to be the immune system’s central communication node, and mice lacking the STAT1 gene died from severe infection, suggesting that this gene is vital in pathogen response." (PMID 36059536, 2022). "Furthermore, we noted that STAT1, STAT2, IRF9 also exhibited high levels of transcription earlier in HuB20 infection than SY18." (PMID 36544767, 2022). "IFN-τ, like IFN-a, has been reported to activate the phosphorylation of STAT1 and induce the expression of numerous ISGs, which might also be antagonized by CPIV3 infection." (PMID 35632770, 2022). "Infection by T. gondii blocks STAT1 mediated transcription, despite not altering STAT1 phosphorylation, dimer formation, nuclear import or DNA recognition." (PMID 35831295, 2022). "Specifically, infection of MAGI1-null ECs with IAV upregulates expression of signal transducer and activator of transcription 1 (STAT1), interferon b1 (IFNb1), myxovirus resistance protein 1 (MX1) and 2′-5′-oligoadenylate synthetase 2 (OAS2), and activate STAT5." (PMID 36082118, 2022). "Virus titration results showed that LASV was present in all Stat1-KO mice even at the end of the study (7 w.p.i.)without any dramatic differences among groups, indicating that LASV caused prolonged infections in Stat1-KO mice." (PMID 35605008, 2022). "Our Q‐PCR data validate this result, and checking the inflammatory‐related signalling transduction pathway activation further confirmed this conclusion because there was enhanced activation of STAT1, NF‐kB and MAPK pathways observed in response to H37Rv infection." (PMID 34632719, 2021). "In addition, we found that phosphorylation of CD3ζ (Tyr83), ZAP70 (Tyr319), and STAT1 (Ser727), as well as the expression of T-bet, was reduced in lung CD4+ T cells of CD4–TREM-2 KO mice upon MHV-A59 infection." (PMID 34878838, 2021). "Ddx3xfl/flLysMCre BMDMs showed a significant reduction in secretion of IFN-β and delayed activation of STAT1 (P-STAT1 levels) compared with Ddx3xfl/fl BMDMs upon IAV and IAV–ΔNS1 infection, further establishing a role for DDX3X in IAV-induced type I IFN responses." (PMID 33766561, 2021). "Interferon Regulatory Factors activate STAT1, STAT2, and STAT3 that stimulate the innate and acquired immune responses, mediate cellular responses to interleukin, and regulate inflammatory responses to infection." (PMID 34207861, 2021). "Following T. crassiceps i.p. infection with 10 cysticerci, we determined the antibody production against T. crassiceps in the serum of STAT1+/+ and STAT1−/− mice obtained at weeks 4 and 8 post-infection to detect specific anti-T. crassiceps IgG1 and IgG2a antibodies." (PMID 34684235, 2021). "Analysis of stool, ileum, colon, MLN, and spleen viral levels in survivors at 14 dpi demonstrated equivalent viral levels in Pou2f3+/-Stat1-/- and Pou2f3-/-Stat1-/-, supporting that CR6F514I infection of intestinal and extraintestinal tissues of Stat1-/- mice is tuft cell-independent." (PMID 33705489, 2021). "From the cytokine profiling of various groups, we can conclude that Peptide8 inhibits the binding of SOCS1 with gp130, restores the phosphorylation of STAT1 and activation of JAK-STAT1 signaling pathway, thereby formation of pro-inflammatory cytokine during infection." (PMID 35011356, 2021).
infection (continued). "The presence of PGPC during infection diminished the production of VSV-G proteins but did not impact the lack of STAT1 phosphorylation observed." (PMID 33849978, 2021). "A375 cells had no baseline p-STAT1(Y701) and responded with p-STAT1(Y701) induction only after PVSRIPO infection." (PMID 33849973, 2021). "In addition, we confirmed that caspase-3 is activated during NH/P68 and Arm/07/CBM/c2 infections in PAM being more pronounced during infection with the virulent strain, which correlated with a more effective degradation of STAT1 with this isolate." (PMID 34512601, 2021). "Furthermore, a gradual up-regulation of IRF7, IRF9, STAT1 and STAT2 genes was observed in Calu-3 cells after the infection with SARS-CoV-2 for 24 h." (PMID 34578229, 2021). "I514 virus can subsequently disseminate rapidly to extraintestinal tissues via non-lymphoid immune cells in the blood in Stat1-/- mice, permitting lethal infection of the brain." (PMID 33705489, 2021). "STAT1 KO spleens were found to average 5–10 times larger than their wild-type (WT) littermates in absence of any notable infection." (PMID 34378531, 2021). "Similarly, infection of STAT1 KO mice with this strain of LASV produced similar levels of uniform and lethal infection." (PMID 34747339, 2021). "Primary SAECs from nondiseased donor lungs apically infected (at the air-liquid interface) with IAV (up to 3×105 pfu; ~1 multiplicity of infection) markedly (eight-fold) boosted the expression of ACE2, paralleling that of STAT1, a transcription factor activated by viruses." (PMID 33419885, 2021). "In order to reveal a possible mechanism involved in the failure to recruit innate immune cells in the absence of STAT1 at 2 days post-infection, we analyzed the expression of CCR2, a chemokine receptor associated with the recruitment of inflammatory monocytes." (PMID 34684235, 2021). "To evaluate such activity in the presence and absence of STAT1, we isolated PECs from STAT1+/+ and STAT1−/−T. crassiceps-infected (2 days after infection) or naïve mice." (PMID 34684235, 2021). "The same phenotypes were observed with RARRES3 ectopic expression irrespective of the presence of STAT1, suggesting that decreased infection on overexpression of RARRES3 is not due to induction of IFNγ signaling." (PMID 34871166, 2021). "More recently, STAT-1 and IFNAR-/- mice have been used as a model of infection." (PMID 33804381, 2021). "The expression of STAT1, JAK1, and JAK2 genes increased following the infection time." (PMID 33240261, 2020). "To address whether the extent of pathway sensitization is cell type‐specific, we examined Roferon‐induced phosphorylation of STAT1 and STAT2 in the nucleus of HepG2‐hNTCP cells, which are commonly used to study infection of hepatitis B virus." (PMID 32696599, 2020). "To test whether CD300lf was essential for parenteral infection routes, we bypassed the gastrointestinal tract by administering 107 PFU MNoVCW3 intraperitoneally (IP) to Cd300lf-/-Stat1-/- mice." (PMID 32251490, 2020). "Increased virus RNA levels in the absence of STAT1 but not RAG1 on day 3 postinfection suggests that during the early stages of infection, IFN-Is rather than adaptive immune cells are critical for inhibiting initial virus replication and spread." (PMID 32310998, 2020). "In the circRNA-miRNA-mRNA network, circRNAs would indirectly regulate 25 chicken mRNAs, such as STAT1/4 and IRF1/7, indicating that these circRNAs might play a critical role in regulating vvIBDV-infection." (PMID 33076825, 2020). "Host genes commonly upregulated upon infection with either Ot strain include IFNB1 (interferon beta) and genes involved in regulating the type-I interferon response: IRF9 (interferon-regulated factor 9) and STAT1/2." (PMID 32620750, 2020).
infection (continued). "However, in response to infection, male mice exhibited higher expression levels of CXCL2 (KO, 1A3, and 6A2), SAMHD1 (1A0, 1A3), RSAD2, STAT1, and STAT3 (1A0), MYD88 and PSMB8 (1A3), BCL3, BCL10, CCRL2, IFITM2, RTP4, and ZFP36L1 (6A2), compared to females." (PMID 32670284, 2020). "Hence, as IFN-I production and signaling is necessary for the development of the lethal disease in LCMV-infected STAT1 KO mice, it remained possible that the survival of STAT1/RAG1 DKO mice following infection was due to impaired IFN-I production." (PMID 32310998, 2020). "Moreover, genes such as Ifr9, Ifr8, Ifr7, CSF2RA, STAT1, and STAT2 were expressed to a greater extent in the PmQ infection group than PmCQ2, and Il22, Il6, Nos2, Ccl4, Ccl5, Ifr1, Socs1, and Socs3 were increased only in PmQ infected chickens rather than PmCQ2." (PMID 32851030, 2020). "FCV 2280 infection did not reduce the expression of total STAT1 and STAT2, but it significantly inhibited the levels of the phosphorylated STAT1 and STAT2 proteins in FCV-infected CRFK cells." (PMID 33075108, 2020). "The two ISGs were elevated after the infection of rRABVs expressing IFN-λ in our study, indicating that IFN-λ could activate the STAT1/2 signaling pathway during RABV infection, resulting in the downstream production of ISGs to restrict RABV infection." (PMID 32268591, 2020). "We show that the expression of the interferon-stimulated proteins MX1, IFIT1, IFIT3 and ISG15, as well as expression of defense response proteins DDX58, STAT1, OAS3, EIF2AK2 and SAMHD1 was significantly up-regulated in these cells upon infection with either virus." (PMID 30959732, 2019). "Focusing on earlier time points, before loss of IFN production/signaling becomes the overwhelming factor affecting infection efficiency, may reveal more subtle differences conferred by abrogation of either IRF3 or STAT1 signaling." (PMID 31921100, 2019). "Interestingly, after IFN-α treatment, the two effects of SFTSV infection on STAT1 (sequestration in NSs IBs and abundance reduction) were found in SFTSV-infected cells as well and consequently STAT1 nuclear accumulation was similarly diminished." (PMID 31191546, 2019). "STAT1 is an ISG and expression of STAT1 increases during infection with SeV." (PMID 31539400, 2019). "In summary, our work extends awareness of the role(s) of the STAT1 and STAT6 pathways in lung healing during acute T. canis infection and highlights the importance of M2 macrophages in accelerating tissue recovery during the lung stage of this infection." (PMID 31810203, 2019). "In contrast to STAT1-deficient mice, mice that lack STAT2 do not develop lethal disease after IP or IC infection with LCMV-Arm, despite both mice showing uncontrolled viral replication and spread." (PMID 30791575, 2019). "In contrast, neither the STAT1 in the mock infection group nor another transcription factor STAT2 exhibited such reduction." (PMID 31191546, 2019). "In addition, Stat1-/-Gsdmd-/- and Stat1-/-Nlrp3-/- mice showed diminished fecal Lcn-2 levels upon gastrointestinal MNV infection." (PMID 31017981, 2019). "Despite efficient infection by a single-cycle HIV-1 strain, none of the cell types showed activation of innate immune markers; they showed neither type I IFN production nor ISG mRNA induction nor STAT1 phosphorylation for up to 3 days after infection." (PMID 30755516, 2019). "Immunocompromised mice, such as interferon receptor or STAT1 knockout mice, develop lethal infections but are not ideal for testing vaccines or characterizing immune responses." (PMID 31554720, 2019). "Our present study demonstrated that translocation of activated STAT1 and STAT3 induced by EV71 infection required KPNA1 in T98G cells, and consistent with a previous study in RD cells, we observed degradation of KPNA1 in T98G cells upon infection." (PMID 31575039, 2019). "We show that SFK inhibition blocks infection in the absence of functional interferon signaling in cells lacking IRF3 or STAT1." (PMID 30917980, 2019).
infection (continued). "These nPro/HFs and V/HFs were recently utilized, alongside IRF3 KO CRISPR/Cas9 HFs, to demonstrate that expression of viperin, ISG15, IFIT1, IFIT2, IFIT3, Mx1, and Mx2 mRNA during infection with HCMV can be induced in an IRF3-dependent, STAT1-independent manner." (PMID 31921100, 2019). "By contrast, infection of TgIST-KO T. gondii did not result in STAT1 Y701-p nuclear translocation in unstimulated cells." (PMID 30283439, 2018). "Induction of the MHC-I gene expression was also evidenced in our experimental model of infection by over-expression of NLRC5, a specific transcriptional activator of the MHC-I expression, induced by IFNγ through STAT1 activation, whose coding genes were observed also over-expressed in this study." (PMID 29391047, 2018). "Stat1 mRNA levels varied between cell preparations and showed no significant changes throughout infection in either cell type." (PMID 29491163, 2018). "Infection with MHV-68 alone did not induce phosphorylation of STAT1, whereas treatment with IFN-γ did." (PMID 30075008, 2018). "As expected, O/03 infection did not result in STAT1 nuclear localization, despite the presence of high levels of antiviral cytokines (24 hpi)." (PMID 29237841, 2018). "However, transcription levels of IFN-β, IFN-λ, ISG56, CCL5, and IL-6, and expression levels of STAT1, pSTAT1, and ISG15 were similar in A549 cells after infection with all 4 recombinant viruses." (PMID 30050872, 2018). "Although EMCV modulated global SUMO2/3 modification, its effect on PKR 2 h and 4 h post-infection seems to be specific since EMCV did not alter the modification of STAT1 that was shown previously to be SUMOylated7,23." (PMID 29352251, 2018). "Interferon-α induced STAT1 phosphorylation was not inhibited nor did eIF2α become phosphorylated 16 h post infection in the presence of silvestrol." (PMID 30380742, 2018). "The phosphorylation of STAT1 was blocked in 60% of cells infected with rNigeria/75/1 by 18 hpi and by 40 hpi almost no infected cells had STAT1P in the nucleus, confirming that infection with the parental virus is blocking the IFN action pathway as previously reported." (PMID 28475628, 2017). "STAT1, STAT2, and/or STAT3 tyrosine phosphorylation has been demonstrated by others to occur in fibroblast cells or macrophages at various times following infection with TC-MCMV." (PMID 28182772, 2017). "UPEC colonization in prostate cells co-incubated with testosterone and JAK1 or STAT1 inhibitor did not decrease 24 h after the infection." (PMID 28665978, 2017). "Moreover, infection with the CA/04-NAK331N or CA/04-NAS79L,K331N virus resulted in decreased activation of STAT1 and reduced expression of RIG-I compared to those induced by infection with the parental CA/04 virus or the CA/04-NAS79L virus." (PMID 28750037, 2017). "However, in an assay of HeLa cell infection and replication, we were unable to show that the coadministration of CRT0066101 enhanced IFNAR signaling, as revealed by STAT1 phosphorylation or by the induction of mRNA expression of the IFN-stimulated gene OAS." (PMID 28228588, 2017). "The infection with A249P-mut and C486F-mut viruses but not with I356T-mut virus, resulted in significantly more efficient inhibition of STAT1 phosphorylation in response to IFN treatment, as compared to the NSW2011 infection." (PMID 29099073, 2017). "STAT1 and IFIT1 upregulation has previously been seen in proteomic analysis of HeLa cells infected with reovirus, suggesting that despite low concentration of LPS, the 3T3-L1 adipocytes exert the same stress-response as during infection." (PMID 27438462, 2016). "Accordingly, in spite of the presence of high levels of viral RNA and IFN-β in brains of IPS-1−/− mice, day 4 post infection, STAT1 phosphorylation was not detectable and neither was ISG expression." (PMID 26819220, 2016).
infection (continued). "The activity of C6 in blocking this pathway was likely to be masked to some degree during infection by the presence of the virus phosphatase VH1, which dephosphorylates STAT1 and STAT2 and is delivered into cells by the invading virion immediately after infection." (PMID 27907166, 2016). "Our data confirm that infection with hrHPV decreases basal STAT1 protein levels in KCs but also show that hrHPV does not interfere with IFNγ-induced STAT1 activation per se, as reflected by STAT1 phosphorylation and increase in RARRES1 and IFITM1 expression." (PMID 27920775, 2016). "We experienced no successful infection and pathogenesis in 2-week old mice in either hSCARB2 transgenic model or the stat-1 KO model." (PMID 27499235, 2016). "Together, these results demonstrate that activation of STAT signaling molecules does not differ significantly early in infection (3 dpi), but that STAT1 and STAT2 phosphorylation occurs later infection in CD46+ and CD46+/IFNγ-KO explants." (PMID 27178303, 2016). "TRP120 and Ank200 target genes of important components of the Jak-Stat pathway, e.g., Jak2, Stat1, Stat3, Stat5, and IFNR2, and thus might be involved in regulation of IFN-γ signaling during infection." (PMID 27303657, 2016). "Consistent with these previous findings we showed here that infection with the non-persistent strain MNV-1.CW3 leads to phosphorylation of Stat1." (PMID 27294868, 2016). "Therefore, we additionally determined that STAT1 is phosphorylated and activated in MEFs following IIV-6 infection." (PMID 27824940, 2016). "The non-persistent strain MNV-1.CW3 led to activation of Stat1 whereas the Stat1 phosphorylation was significantly decreased after infection with MNV-S99 (p = 0.0148)." (PMID 27294868, 2016). "Since PML interacted with STAT1, STAT2, HDAC1, and HDAC2, we investigated whether IE1 simultaneously interacts with PML, STAT1, STAT2, and HDACs during infection." (PMID 25812002, 2015). "In support of this hypothesis, KD of STAT1 prevents CVB-induced MX1 expression in α cells and enables a more active infection with CVB5, as evaluated by higher expression of the enteroviral capsid protein VP1." (PMID 26061776, 2015). "For example STAT1 can be activated by type I interferon, STAT3 can be activated by growth factors (e.g. EGF, LIF) and NFκB can be activated by reactive oxygen species, infection and other inflammatory cytokines, including IL-1β." (PMID 26678048, 2015). "IFN-γ prestimulation of WT and Cyld−/− BMDM without infection resulted in an equally weak activation and nuclear translocation of STAT1, a critical IFN-γ-induced transcription factor." (PMID 26834734, 2015). "We showed that all STAT genes (STAT1-4, 5a, 5b, and 6) are expressed in alveolar macrophages, with STAT1 and STAT2 having 10- to 200-fold higher expression levels than other STAT transcripts at 16 h post PRRSV-infection (, unpublished data)." (PMID 26213635, 2015). "Furthermore, in bothA549 and T84 cells, HPeV1 downregulated the activation of STAT1, downstream of IFN,and antiviral gene expression; this innate immune evasion should be critical forHPeV1 infection." (PMID 25646764, 2015). "Infection alone was not sufficient to trigger STAT1 activation, whereas a 15-min stimulation with IFN-γ triggered phosphorylation of STAT1 in nearly every infected and uninfected cell." (PMID 26196739, 2015). "Recently, it has been shown that influenza virus-induced SOCS1 is independent of cytokine at early stages of infection both in vitro and in vivo, remarkably suppresses the activation of STAT1." (PMID 26206138, 2015). "In SOCS-1 knockdown A549 cells, but not the control cells, the level of STAT1 phosphorylation was notably increased during the infection, indicating that SOCS-1 was a direct inhibitor of STAT1 phosphorylation during IAV infection." (PMID 24391501, 2014). "Although, it is unknown how IRF-1 is induced in detail, STAT-1 was identified as an upstream inducer of IRF-1 in VSV and KSHV in vitro infection models." (PMID 24675692, 2014).